IL10 (interleukin 10)
Diseases named in the same sentence as IL10 in open-access papers (continued):
Sharing a sentence is not in itself a finding about the gene and the disease.
diabetes (continued). "Unlike what happened when treating diabetic rats with ADA, ADORA3 antagonism does not significantly affect the levels of IL-10, while only attenuates the levels of IL-6 found in diabetes." (PMID 31540220, 2019). "Finally, vaccination in combination with PPI+TGFβ+IL10 and anti-CD3 mAb was found to be most effective and specific in reversing new onset diabetes." (PMID 30863412, 2019). "Patients with type 2 Diabetes mellitus (DM2) who consumed fermented milk without probiotics exhibited reductions in interleukin-10 (IL-10) (p=0.001) and a tendency to reductions in adiponectin (p=0.07), both of which have anti-inflammatory functions." (PMID 31447899, 2019). "Taken together these data suggested that in vivo treatment of IL-33 may have beneficial effects in MLD-STZ diabetes by promoting Tregs and in particular ST2+ Tregs producing IL-10 and possibly IL-5 and/or IL-13." (PMID 30498495, 2018). "Interestingly, with ANOVA analysis, the exercise significantly increased circulating inflammatory markers (IL-1β, IL-6, TNF-α, and IL-10) and decreased WBC, while diabetes displayed significant effect on HR and TNF-α." (PMID 29467719, 2018). "Administration of DCs prepared in the presence of interleukin 10 (IL-10) with or without antigen supply both prevented diabetes and insulitis in NOD mice." (PMID 29503651, 2018). "Based on the literature review, there are no known studies that demonstrate diabetes and metabolic syndrome influencing levels of IL-10 and modulating outcomes in MI." (PMID 30356307, 2018). "When cytokine levels were measured 14 weeks after diabetes induction, a clear shift toward a Th1 pattern was present, characterized by higher IFN-γ and IL-2 secretion (respectively, p < 0.001) and lower IL-4 (p < 0.05) and IL-10 levels (p < 0.01)." (PMID 28851944, 2017). "NOD mice, which develop diabetes spontaneously, were immunized twice using papillomavirus like particles 14 days apart, with or without neutralizing IL-10 antibody." (PMID 28810829, 2017). "Exactly how these diabetes medications interact with hyperglycemia to impact IL10 function is not known." (PMID 26883847, 2016). "No changes in plasma levels of OPN, IL-10, TNFα, IL-12p70, IL-1β, IL-6, and KC were observed in response to diabetes or NFAT inhibition; however plasma IFN-γ was reduced in diabetic animals that had been treated with A-285222." (PMID 25918731, 2015). "Glucose serum concentration at the time of blood sample, age, BMI, sex, diabetes duration, and HbA1c were not significantly correlated with IL-6 and IL-10 concentration." (PMID 25961054, 2015). "Thus, WP supplementationduring diabetes significantly restored the levels of TNF-α, IL-1β,IL-6 and IL-10." (PMID 22708778, 2012). "A previous study demonstrated that absence of IL-10 failed to accelerate spontaneous diabetes but potentiated cyclophosphamide-induced diabetes in non-obese diabetic mice." (PMID 23285260, 2012). "Conversely, we found that LTA-treated DCs produced much more IL-12 than IL-10, and without upregulating high expression of B7-1 or B7-2 accelerated diabetes when injected into NOD mice." (PMID 21716731, 2011). "Several studies have reported decrease in diabetes incidence following one injection of DCs whose cytokine profile was modulated to produce IL-10 and not IL-12." (PMID 21716731, 2011). "SCID mice accelerates diabetes, demonstrating that pancreatic IL-10, not peripheral IL-10, appears to play a role in diabetes pathogenesis." (PMID 21716731, 2011). "For example, overexpression of IL-10 in islet cells in a nonobese diabetic mouse model exacerbates diabetes and, recent data indicate that ApoE can stimulate dendritic cells to present lipids." (PMID 20445733, 2010). "have been most often reported in diabetes, EAE and uveitis, whereas in the atherosclerosis model, IL-10 producing Tr1 cells may be the major subtype involved." (PMID 22069660, 2010).
diabetes (continued). "Similarly, immunosuppressive cytokine secretion, including increased IL-10 secretion, was observed after oral administration of CTB conjugated to insulin, resulting in suppression of diabetes onset in NOD mice." (PMID 22069653, 2010). "However, no significant increase in the frequency of S‐specific CD8+ T cells secreting only IL‐10 (and not any other cytokine assessed) was observed in the diabetes groups compared with ND." (PMID 41367201, 2025). "Following adjustment for age, sex, triglyceride levels, diabetes, and hypertension, a covariate variance analysis revealed significant differences between these groups with respect to plasma levels of TWEAK, TNF-α, IL-10, and IL-4 (PTWEAK = .017, PTNF-α < .001, PIL-10 = .010, PIL-4 = .016)." (PMID 40629651, 2025). "A negative correlation between IL-10 and lipids was identified in individuals with diabetes." (PMID 40564977, 2025). "In addition, studies have demonstrated a negative correlation between IL-10 expression and patient age at the time of diabetes diagnosis." (PMID 38542165, 2024). "A higher IL-6/IL-10 ratio was found in patients with diabetes than the values observed in the group without diabetes at T0 (p = 0.029) and T1 (p = 0.025), whereas an increased IFN-γ/IL-10 ratio was only found at T1 in patients with diabetes compared to the group without diabetes (p = 0.041)." (PMID 39253540, 2024). "Dogs with uncontrolled diabetes did not have a different supernatant concentration of IL-10 compared to dogs with controlled diabetes (p = 0.91), with a median of 1986 pg/mL (IQR, 328–3205; range, 49–6270 pg/mL) and 1537 pg/mL (IQR, 360–3206; range, 49–8170 pg/mL), respectively." (PMID 38787165, 2024). "Additionally, a study conducted on human patients with a diagnosis of type 2 diabetes mellitus (T2DM) treated with sitagliptina, a linagliptin analog, for approximately 48 weeks, showed significant increases in IL-10 levels in circulating monocytes in peripheral blood." (PMID 39518925, 2024). "In addition, it has been shown that B lymphocytes secrete proinflammatory cytokines, including IL-8, along with a decrease in IL-10 production, compared to B cells from subjects without diabetes." (PMID 36678282, 2023). "The role of hsa-miR-503 in pathomechanism of diabetes complications depends on mitochondrial activity (DHFR), cell cycle control (CCNE2), cell protection (SOD2), podocyte migration (ANLN), inflammatory process (IL10, EFE2, VEGFA) and fibrosis (COL1A1), showing its contribution to CKD development." (PMID 36859746, 2023). "In this study, we first presented markedly elevated Th1 cytokine IL-2R and TNF-α levels and increased levels of Th2 cytokines, including IL-6, IL-8, and IL-10, in patients with diabetes compared with patients without diabetes among patients with COVID-19 pneumonia." (PMID 33776910, 2021). "Finally, i.p. application of GM-CSF + IL-10-generated (without MPLA activation) tolDCs loaded with immunodominant insulin B chain peptides prevented diabetes in NOD mice by in situ induction of Foxp3+ Tregs, when cultured in autologous mouse serum." (PMID 29503651, 2018). "Seventeen patients with type 2 diabetes mellitus under clinical management weresubmitted to surgery and blood samples were collected before and six months aftersurgery for evaluation of the serum profile of proinflammatory (IFN-γ, TNF-α,IL-17A) and anti-inflammatory cytokines (IL-4, IL-10)." (PMID 26734798, 2015). "Altered B cell functioning in diabetes mellitus patients leads to increased inflammation via the following two mechanisms: increased pro-inflammatory IL-8 production and a lack of anti-inflammatory/protective IL-10 production." (PMID 26270535, 2015). "In accordance with our results, EGCG, the primary polyphenolic component of green tea, has been shown to significantly elevate the level of the circulating anti-inflammatory cytokine IL-10 and to effectively delay the onset of diabetes in non-obese diabetic mice." (PMID 26270535, 2015).
diabetes (continued). "Interestingly, LL-GAD CT retained a similar 60% diabetes remission even in severely hyperglycemic (late) NOD mice as opposed to LL-PINS+IL-10 CT." (PMID 25185797, 2014). "We had previously shown long-term reversal of diabetes in NOD mice using ATG or ATG in combination with G-CSF and our current findings in this report provide a mechanistic basis for this in the skewing toward Th2 and/or IL-10-producing Tr1 responses under the regimen of ATG." (PMID 23237483, 2012). "Other cytokines including TNFα, IL-10, and IL-12 did not change with diabetes control." (PMID 22924123, 2012). "Intriguingly, the neutralization of one of these two cytokines (IL-10 or TGF-β) just had minor effects on Treg-mediated blockade of diabetes development (data not shown), indicating a complementary role of IL-10 or TGF-β in mediating Treg protective effects when one cytokine was removed." (PMID 19759824, 2009). "Consequently, a refined selection comprising seven genes (MMP2, MMP9, IL17A, IL10, FGF2, IL6 and VEGFA) and eleven pharmacological agents has emerged, exhibiting promise in delivering therapeutic effects aimed at mitigating the occurrence of OP in individuals afflicted with diabetes." (PMID 38250601, 2024). "However, diabetes did not significantly alter the release of IL-6 and IL-10 in CABG patients." (PMID 35935655, 2022). "Because tDCs are often seen to release IL-10, TGF-β, and retinoic acid, stable Tregs will, in turn, affect the tDC tolerance status through intercellular interactions and paracrine immunomodulatory cytokines, which may result in much more effective and long-term protection from diabetes." (PMID 35563276, 2022). "Also, gut bacteria stimulate IL-10 production and maternal antibiotics intake in non-obese diabetic (NOD) mice increases the risk of diabetes development in new-borns whereas low intrauterine gluten exposure and vitamin D3 supplements in human infants decrease the risk to develop T1D." (PMID 35903316, 2022). "In addition, IL-10-producing B cells (regulatory B10 cells) attenuate autoimmune, inflammatory reactions, through IL-10 production and the administration of IL-10 can suppress collagen-induced arthritis, as well as the diabetes of non-obese diabetic (NOD) mice." (PMID 28455817, 2017). "The non-response cohort was older, more likely to have diabetes, and had higher levels of D-D polymers, Pro-BNP, direct bilirubin, and inflammatory markers, including ferritin, C-reactive, procalcitonin, IL-6, IL-10, and IL-17A than the response cohort." (PMID 41426569, 2025). "Injection of IL-10 alone did not protect NOD mice from diabetes which might indicate that rapamycin first needs to reduce effector T cell proliferation before IL-10 is able to maintain a stable Tr1 cell population, as illustrated by a synergistic effect of rapamycin and IL-10 treatment." (PMID 36389662, 2022). "Our data showed that in the absence of IL-10, BDC2.5+ NOD mice develop accelerated diabetes at a very young age." (PMID 34394099, 2021). "At 24 h, 48 h and 72 h post-infection, the levels of IL-1Ra, IL-6, IL-8, IL-10, IL-12p40, TNF-α, MCP-1, and MIP-1b were still low in ESRD without diabetes group than in the control group." (PMID 31875015, 2019). "Apart from IL-10, no other changes in cytokine levels in retina or in the expression of ICAM-1 mRNA in retinal vessels were observed in response to diabetes, at least at these early time points and in these mice strains." (PMID 25918731, 2015). "Although IL10-deficient NOD mice are not readily available, it would be interesting to test whether BM-DCs from IL-10-deficient NOD mice are capable of preventing diabetes, or whether feeding Lactobacilli to IL-10-deficient NOD mice can still affect diabetes development." (PMID 21716731, 2011).
diabetes (continued). "Non-surviving patients also showed a higher incidence of diabetes mellitus (P = 0.02), higher lactatemia (P < 0.001), higher SOFA (P < 0.001) and APACHE-II (P < 0.001) scores, and lower platelet count (P = 0.002) and IL-10 (P < 0.001) than surviving patients." (PMID 21406105, 2011). "Thus, increased expression of IL‐21 and IL‐10 was detected in people with T1D compared with ND (31% and 37% of IL‐10‐producing CD8+ T cells in T1D and T2D participants, respectively, compared with 12% in people without diabetes)." (PMID 41367201, 2025). "There was no meaningful difference in the levels of IL-10 and VEGF when we looked at patients in this group based on whether they had diabetes, high blood pressure, smoked, or had certain genetic risks." (PMID 40647640, 2025). "In the group with diabetes, it was verified positive correlations between IL-10 and IL-6 or IFN-γ and a negative correlation between IL-6 and PMP, at T0; in contrast, in the T1, negative correlations were found between TNF-α and IL-10 or PMP." (PMID 39253540, 2024). "Although these data, again, can reinforce the pro-inflammatory feature of diabetes, the lack of significant difference in the IFN-γ/IL-10 ratio 30 days after the periodontitis treatment ends (T1) can demonstrate that this procedure was able to impact this ratio, apparently in the non-diabetic group." (PMID 39253540, 2024). "Regarding the group with diabetes, at baseline (T0), it was evidenced positive significant correlations both between circulating levels of TNF-α and IL-6, and between levels of IL-10 and EMP, as well as a negative significant correlation between IL-10 and PMP." (PMID 39253540, 2024). "Besides, at T0, it was evidenced positive correlations both between circulating TNF-α and IL-6, and IL-10 and EMP, as well as a negative correlation between IL-10 and PMP in the group with diabetes." (PMID 39253540, 2024). "At 6 h post-infection, IL-2 and GM-CSF were detected at higher concentrations, but there was a significant reduction of stimulated mononuclear cell production of IL-8, IL-10, IL-12p40, TNF-α, MCP-1, and MIP-1b in ESRD without diabetes group than in control group." (PMID 31875015, 2019). "In 4-week-old non-diabetes prone B6 mice, which do not accumulate TI-IFN in pancreatic and mesenteric lymph nodes, Tmem and Treg preserved their ability to fully respond to IL-10 in all lymphoid tissues." (PMID 30061883, 2018). "Production of anti-inflammatory cytokines such as IL-10 and TGF-β is known to suppress development of diabetes in NOD mice, and it is not surprising that a reduction in the production of anti-inflammatory cytokines could precipitate disease." (PMID 26783747, 2016). "Moreover, non-diabetic plasma-treated SVFs are capable of mitigating diabetes-induced plasma DPP4 activity, liver inflammation, and insulin resistance, which may be mediated by suppressing M1 cytokines and increasing IL-10 and Tregs in the adipose tissue." (PMID 39125659, 2024). "Most importantly, our findings reveal that nondiabetic plasma-treated SVFs are capable of mitigating diabetes-induced plasma DPP4 activity, liver inflammation, and insulin resistance and that may be mediated through suppressing M1 cytokines but increasing IL-10 and Tregs in adipose tissue." (PMID 35883204, 2022).
Autoimmunity (345 papers, 2008 to 2026). The occurrence of an immune reaction against the organism's own cells or tissues. "B cells are central to immune tolerance induction, with various subsets capable of downregulating inflammatory responses associated with autoimmunity and transplant rejection, primarily through IL-10 production." (PMID 41453995, 2025). "Older mice with TIM1 mutation showed decreased IL-10 secretion from B cells, spontaneous autoimmunity associated with T cell overactivity, increased IFNγ production, and elevated serum Ig and autoantibody levels." (PMID 40075055, 2025). "In another study, this relationship with inflammatory patterns resulted in a positive association between AMY1 CN and IL-10, which is known to play a role in anti-inflammatory functions and preventing autoimmune disorders." (PMID 39953449, 2025). "This mutation leads to a defective receptor, impairing the IL-10 signaling pathway and thus contributing to chronic inflammation and autoimmunity." (PMID 39539768, 2024). "In patients treated for Lyme arthritis, ongoing inflammation and autoimmunity responses were associated with high pro-inflammatory IFN-γ concentrations in combination with low IL-10 levels." (PMID 38515037, 2024). "These cells produce large amounts of cytokines IL-10 and IL-17, and have been suggested to be implicated in the control of autoimmunity and inflammation." (PMID 37928672, 2023). "Evidence shows the protective function of IL-10 against autoimmunity by controlling pathogenic Th17 differentiation." (PMID 37834058, 2023). "IL-10 inhibits the production of proinflammatory cytokines as shown by the development of hyper-inflammation and autoimmunity in IL-10-deficient mice." (PMID 36970418, 2023). "While the IL-10 effects can be considered as causing a decreased ability to fight infections, it is likely to play a protective role in autoimmunity and tissue damage." (PMID 35317169, 2022). "CD4 effector T-cell cluster 7 correlated inversely with autoimmunity to IA-2, while higher IL-10 response to the vaccine peptide associated with lower (i.e., improved) HbA1c values." (PMID 36505460, 2022). "Adoptive transfer of TGF-β-producing B cells (Bregs) to attenuate disease related autoimmunity by targeting pathogenic cells and secretion of IL-10." (PMID 34987468, 2021). "Th17 cells have been implicated in the development of autoimmunity, whereas Treg cells producing IL‐10, IL‐35, and TGF‐β maintain self‐tolerance and protect against thyroid autoimmunity." (PMID 33943012, 2021). "In murine models of autoimmunity, IL-10 deficiency demonstrated disease exacerbation, while IL-10 overexpression illustrated immunosuppressive properties." (PMID 32824387, 2020). "IL-10 is an immunosuppressive cytokine (involved in the peripheral immune tolerance); IL-10-deficient mice have been shown to develop a variety of inflammatory and autoimmune conditions." (PMID 30674337, 2019). "Here, we review the impact of altered miRNA levels on the expression of cytokines that play a relevant pathogenic role in autoimmunity, namely primary pro-inflammatory cytokines, the IL-17/IL-23 axis, type I interferons and IL-10." (PMID 30761124, 2019). "Increasing evidence has linked dysregulated interleukin (IL)-10 production by IL-10+ve B cells to autoimmunity, highlighting the importance of improving the understanding of the regulation of IL-10 production in these cells." (PMID 29229781, 2018). "Although the effect of these losses on autoimmunity was modest in B6.NZBc4 mice, other groups have shown that the gain or loss of IL-10 competent regulatory B or NKT cells can have profound effects on disease." (PMID 26964093, 2016). "Forced expression of EGR2 in naïve T cells converts them into LAG3 expressing and IL-10 secreting regulatory cells while EGR2 deficiency results in lupus-like autoimmunity, as well as increased STAT3 phosphorylation and IL-17 secretion." (PMID 25880134, 2015).